ALK (ALK receptor tyrosine kinase)
Diseases named in the same sentence as ALK in open-access papers (continued):
Sharing a sentence is not in itself a finding about the gene and the disease.
non-small cell lung carcinoma (continued). "Another interesting case was discussed in 2011, pertaining to the application of a product for the treatment of ALK-positive non-small cell lung cancer." (PMID 24461084, 2014). "Rearrangements of anaplastic lymphoma kinase (ALK) have been recently identified in non-small cell lung carcinomas." (PMID 25295103, 2014). "The efficiency of targeted cancer therapies in drug-sensitive genotypes such as HER2 amplified breast cancer, B-Raf mutant melanoma and ALK translocated non-small cell lung cancer (NSCLC) is significantly inhibited by treatment resistance." (PMID 25238228, 2014). "In fact, Crizotinib has been approved by the FDA for the treatment of ALK+ non-small cell lung cancer." (PMID 25386922, 2014). "For example, approximately 4% of non-small-cell lung cancers express the EML4-ALK fusion protein, providing a marker for responsiveness to the ALK kinase inhibitor crizotinib." (PMID 25594012, 2014). "Crizotinib, a tyrosine kinase inhibitor already in clinical testing for MET kinase-driven tumors, was known to inhibit also ALK kinase and trials were therefore extended to target EML4-ALK-positive non-small cell lung cancer (NSCLC) patients." (PMID 25520658, 2014). "Patients with metastatic non-small cell lung cancer are routinely tested for EGFR mutations and rearrangements of the gene encoding the ALK tyrosine kinase receptor/anaplastic lymphoma kinase (ALK) to guide treatment." (PMID 25198155, 2014). "ASP3026 is a second-generation ALK inhibitor that can overcome crizotinib resistance in non-small cell lung cancer, and is currently being evaluated in clinical trials of patients with ALK+ solid tumors." (PMID 25026277, 2014). "The ALK-inhibitor crizotinib is approved for the treatment of ALK-rearranged non-small cell lung cancer." (PMID 25593991, 2014). "The fusion of echinoderm microtubule-associated protein-like 4 (EML4) and ALK gene by rearrangement in non-small cell lung cancer was identified and developed as a target of the ALK tyrosine kinase inhibitor, crizotinib." (PMID 24885886, 2014). "Most recent examples include ALK inhibitors in non-small cell lung cancer with an ALK rearrangement or BRAF inhibitors in melanoma with a BRAF mutation." (PMID 24931142, 2014). "This situation prompted us to investigate two ALK IHC antibodies (using a novel ultrasensitive detection-amplification kit) and an automated ALK FISH scanning system (FDA-cleared) in a series of non-small cell lung cancer tumor samples." (PMID 25248157, 2014). "The rate of the anaplastic lymphoma kinase (ALK) gene rearrangements in non-small cell lung cancer (NSCLC) tissues is 3%-5%." (PMID 25539610, 2014). "This approval was dependent on response rates of 50 - 61% from 255 ALK-rearranged non-small cell lung cancer patients enrolled in two single-arm trials." (PMID 25193856, 2014). "Crizotinib is an orally bioavailable small molecule inhibitor of Met and anaplastic lymphoma kinase (ALK), which has been US FDA approved for the treatment of ALK-positive non-small cell lung cancer." (PMID 25534569, 2014). "For example, crizotinib, a first-in-class dual ALK and c-Met inhibitor, has been shown to be particularly effective against ALK positive non-small-cell lung carcinoma." (PMID 24335618, 2013). "We conducted the ALK fusion analyses on 95 formalin-fixed paraffin-embedded (FFPE) tumor tissues from 87 patients with non-small cell lung carcinoma." (PMID 24764475, 2013). "A fusion gene that joins the echinoderm microtubule-associated protein-like 4 (EML4) gene with the anaplastic lymphoma kinase (ALK) gene was found in a subset of non-small-cell lung carcinomas (NSCLCs) in 2007." (PMID 23922677, 2013). "Anaplastic Lymphoma Kinase (ALK) positivity represents a novel molecular target in a subset of Non-Small Cell Lung Cancers (NSCLC)." (PMID 23359795, 2013).
non-small cell lung carcinoma (continued). "Accurate identification of patients with ALK-positive non-small cell lung cancer (NSCLC) is essential for the clinical application of ALK-targeted therapy." (PMID 23741400, 2013). "Anaplastic lymphoma receptor tyrosine kinase (ALK) gene rearrangements occur in a subgroup of non-small cell lung carcinomas (NSCLCs)." (PMID 23484153, 2013). "Chromosomal translocations, resulting in fusion oncogene of ALK have also been described in multiple cancers such as non-small cell lung cancer, inflammatory myofibroblastic tumours, and others." (PMID 24163262, 2013). "In this regard, we note that ROS1 tyrosine kinase is sensitive to the existing ALK small-molecule inhibitor, crizotinib, and indeed a single patient's non-small cell lung cancer harboring a ROS1 fusion was found to be responsive." (PMID 23637631, 2013). "Crizotinib is approved for ALK rearranged relapsed non-small cell lung cancer with most patients treated in the initial expanded cohort phase 1b study acquiring durable responses." (PMID 23617826, 2013). "Rearrangement in this gene (ALK+) has a role in the oncogenesis of non-small cell lung carcinomas (NSCLs), especially adenocarcinomas." (PMID 22911523, 2012). "Anaplastic lymphoma receptor tyrosine kinase (ALK) gene rearrangements have been reported in 2-13% of patients with non-small cell lung cancer (NSCLC)." (PMID 23198868, 2012). "Crizotinib, a dual MET/ALK inhibitor, has demonstrated promising clinical activity in patients with non-small-cell lung cancer and inflammatory myofibroblastic tumors harboring ALK translocations." (PMID 22034911, 2011). "In separate studies, we demonstrated that crizotinib has relatively modest potency in ALK-positive non-small-cell lung cancer cell lines." (PMID 22034911, 2011). "Use of this technique has also confirmed that, in non-small cell lung cancer, the fusion of ALK appears to occur solely with EML4, as previously reported, rather than with other genes." (PMID 20624322, 2010). "RACE-coupled PCR sequencing was used to assess ALK fusions in a cohort of 103 non-small cell lung carcinoma (NSCLC) patients." (PMID 20624322, 2010). "EML4 fusions with the anaplastic lymphoma kinase (ALK) occur in a subset of non-small cell lung cancers and adenocarcinomas of the lungs." (PMID 19014691, 2008). "Importantly, longitudinal biopsy samples from ALK-rearranged non-small cell lung cancer patients with cancer progression revealed elevated expression of E-cadherin and EpCAM during chemotherapy." (PMID 41679471, 2026). "Furthermore, membrane HER3 was upregulated by tyrosine kinase inhibitor treatment in non-small-cell lung cancer cell lines harboring specific driver mutations, including EGFR-activating mutations, ROS1 fusions, and ALK fusions." (PMID 41752065, 2026). "Hepatotoxicity is a known side effect of ALK inhibitors in non-small cell lung cancer." (PMID 41623453, 2026). "Anaplastic lymphoma kinase (ALK) rearrangement is a well-established oncogenic driver alteration in non-small cell lung cancer (NSCLC), and ALK tyrosine kinase inhibitors (TKIs), particularly lorlatinib, have significantly improved the prognosis of ALK-positive NSCLC patients." (PMID 42187575, 2026). "Top 10 productive authors related to ALK-TKI in the treatment of Non-small cell lung cancer." (PMID 40894217, 2025). "While commonly found and successfully targeted in non-small cell lung cancer, ALK alterations have been recently reported in a subset of NETs, including patients with pulmonary NETs (5.2%), with successful treatment with crizotinib, a selective ALK inhibitor." (PMID 41303577, 2025). "Tyrosine kinase inhibitors targeting ALK structural aberrations (ALK-TKIs) have emerged as a cornerstone in the treatment of ALK-positive malignancies, particularly non-small cell lung cancer, evolving from first-generation Crizotinib to third-generation Lorlatinib." (PMID 41614760, 2025).
non-small cell lung carcinoma (continued). "Although five ALK tyrosine kinase inhibitors (TKIs) have been approved for the treatment of ALK-positive non-small cell lung cancer, the sensitivity of these newly discovered rare ALK fusion variants to ALK TKIs remains unclear." (PMID 40054123, 2025). "For instance, in non-small lung cell cancer (NSCLC), patients with an epidermal growth factor receptor (EGFR) gene mutation or ALK gene fusion may receive MTDs." (PMID 40160883, 2025). "Clinical trials have demonstrated that combining luminespib with ALK inhibitors in ALK inhibitor-resistant non-small cell lung cancer (NSCLC) improved the clinical response, and that HSP90 inhibitors also restored sensitivity to BRAF/MEK inhibitors in resistant melanoma models." (PMID 40872476, 2025). "Since the discovery of the first-generation ALK inhibitor, many other tyrosine kinase inhibitors have been demonstrated to be effective in the first line or further lines of treatment in patients with advanced non-small cell lung cancer with EMLA4-ALK translocation." (PMID 39796163, 2025). "Anaplastic lymphoma kinase (ALK) rearrangements account for approximately 3%–5% of non-small cell lung cancer (NSCLC), and the echinoderm microtubule-associated protein-like 4 gene (EML4) and ALK fusion (EML4-ALK) is the most common ALK rearrangement in NSCLC patients." (PMID 40297141, 2025). "In a more recent example, oral ALK kinase inhibitors became first line therapy for ALK-fusion positive non-small cell lung cancer after several studies showed similar efficacy and significantly improved side effects and quality of life for patients on ALK inhibitors compared to chemotherapy." (PMID 40831936, 2025). "Alterations in the ALK gene, most often fusions, drive cell growth and proliferation and have been identified in a number of cancers, including anaplastic large cell lymphoma, non-small-cell lung carcinoma (NSCLC), and neuroblastoma." (PMID 40862786, 2025). "Top 10 high-cited references related to ALK-TKI in the treatment of Non-small cell lung cancer." (PMID 40894217, 2025). "Similarly, in patients suffering from EGFR/ALK wild-type metastatic non-small-cell lung carcinoma, durvalumab and tremelimumab together with chemotherapy showed better OS and PFS benefit relative to chemotherapy in the phase III POSEIDON trial (NCT03164616)." (PMID 40918459, 2025). "Top 10 productive journals related to ALK-TKI in the treatment of Non-small cell lung cancer." (PMID 40894217, 2025). "Anaplastic lymphoma kinase (ALK) is an important molecular marker of non-small-cell lung cancer." (PMID 38674402, 2024). "Similarly, ALK inhibitors are now commonly used to treat ALK-positive non-small cell lung cancer (NSCLC) based on genetic profiling." (PMID 39795930, 2024). "Appropriate sequential therapies may yield a prolonged response with a satisfactory quality of life in patients with advanced ALK-rearranged non-small cell lung cancer." (PMID 38961982, 2024). "Platinum-based doublet chemotherapy is still the current standard of care for advanced non-small-cell lung cancer (NSCLC) patients who do not have an epidermal growth factor receptor mutation or anaplastic lymphoma kinase (ALK) rearrangement." (PMID 38291048, 2024). "It was instrumental in identifying potential MTDLs targeting the epidermal growth factor receptor (EGFR) and ALK tyrosine kinase receptor (ALK) in non-small-cell lung cancer (NSLC), as well as pan-agonists for dopamine receptors (DRD1–DRD5) for the treatment of neurodegenerative diseases." (PMID 39125808, 2024). "There have been reports of coexisting mutations in the epidermal growth factor receptor (EGFR) and anaplastic lymphoma kinase (ALK) fusion genes in non-small cell lung cancer, but case of EGFR mutation following an ALK mutation has not been mentioned." (PMID 39147711, 2024).
non-small cell lung carcinoma (continued). "Approximately 3–5% of non-small cell lung cancers (NSCLC) harbor ALK fusion genes and may be responsive to anaplastic lymphoma kinase (ALK) tyrosine kinase inhibitors." (PMID 38829559, 2024). "Although EML4–ALK fusions are observed in only 4%–5% of yearly diagnosed non-small cell lung cancer cases, the remarkable response to ALK inhibitor drugs has led to universal testing for all patients with advanced non-small cell lung cancer." (PMID 38894711, 2024). "While the data on the use of ALK inhibitors in ESCC are limited, five ALK inhibitors have been approved for the treatment of non-small-cell lung cancer with an ALK rearrangement, and while the outlook has significantly improved, the emergence of drug resistance remains a significant challenge." (PMID 39518064, 2024). "Similarly, it has been reported that the percentage of ALK-positivity in anaplastic lymphoma kinase (ALK)-positive non-small cell lung cancer (NSCLC) is correlated with response and survival." (PMID 38957324, 2024). "The patient was enrolled in study entitled "a phase II, multicenter, open-label, dual-cohort study to evaluate the efficacy and safety of LORLATINIB monotherapy in ALK inhibitor-treated locally advanced or metastatic ALK-positive non-small cell lung cancer patients in China"." (PMID 38344203, 2024). "Intracranial activity is not limited to ALK-rearranged or EGFR-mutant non-small cell lung cancer." (PMID 38012621, 2023). "In addition, considering ALK stimulates central and peripheral nerve development, ALK inhibitors have been found to play a role in the maturation of non-small cell lung cancer because." (PMID 37745860, 2023). "Atezolizumab has recently been approved for first-line treatment of high PD-L1 expression metastatic Non-Small-Cell Lung Cancer (NSCLC) patients with no EGFR or ALK mutations, on the basis of the IMpower110 trial." (PMID 36647072, 2023). "The present study describes the case of a patient with ALK-positive non-small cell lung carcinoma and thyroid metastases who exhibited a minimal response to ALK inhibitor therapy in the primary lesion, but had a complete pathological response in the thyroid, as confirmed by a thyroid biopsy." (PMID 37927354, 2023). "With the previous success of combating ALK+ non-small-cell lung cancers with ALK tyrosine kinase inhibitors (TKIs), crizotinib, a first-generation ALK-TKI, was officially approved by the U.S. Food and Drug Administration in 2020, to treat unresectable ALK+ IMT." (PMID 37938503, 2023). "Herein, inspired by the work of the Nathanael S. Gray Group at Harvard Medical School, we report our study on the design, synthesis, and evaluation of new EGFR/ALK dual-target inhibitors containing sulfoxide and a cyclopropyl group for the treatment of non-small-cell lung cancer." (PMID 36903251, 2023). "For example, the identification of EML4 > ALK gene fusions in non-small cell lung cancer paved the way for the development of ALK inhibitors and recently drugs targeting tumors of any cancer type with gene fusions involving NTRK genes have been approved by the FDA43,44." (PMID 37400526, 2023). "As ICIs have become an essential treatment modality in non-small cell lung cancer (NSCLC) treatment for those patients without EGFR or ALK mutations, it becomes necessary to develop reliable methods of predicting and monitoring immune responses to these drugs." (PMID 37638022, 2023). "ALK inhibitors have proved an efficacious modality for targeted cancer therapy since the launch of crizotinib in 2011 for the clinical treatment of ALK-positive non-small cell lung cancer (NSCLC)." (PMID 37175956, 2023). "The Food and Drug Administration (FDA) has granted fast approval to the drug ALC for treating people suffering from ALK-positive non-small-cell lung cancer (NSCLC) and experiencing resistance to crizotinib, or if their disease has progressed despite therapy with crizotinib." (PMID 36984441, 2023).
non-small cell lung carcinoma (continued). "Alectinib is a highly selective, second-generation tyrosine kinase inhibitor (TKI) of the anaplastic lymphoma kinase (ALK), which is constitutively activated via gene translocation and serves as the driver oncogene in approximately 4–5% of non-small-cell lung cancers (NSCLC)." (PMID 35681698, 2022). "RET is a new driver gene discovered after EGFR and ALK in non-small cell lung cancer." (PMID 35211155, 2022). "In its recent annual report, the agency published aggregated reports for MPs in some therapeutic areas of interest, such as chronic hepatitis C, age-related macular degeneration, family hypercholesterolemia (PCSK9), and non-small lung cell cancer ALK-inhibitors." (PMID 35782579, 2022). "Examples include EGFR, ALK, ROS1 and RET alterations in non-small cell lung cancer, rendering tumors susceptible to tyrosine kinase inhibitors, or high microsatellite instability/deficient mismatch repair (MSI-H/dMMR) in gastrointestinal tumors, which is associated with response to PD1 inhibition." (PMID 36687417, 2022). "Likewise, 4-5% of non-small-cell lung cancers have a translocation of the ALK gene, which can be effectively targeted by the ALK inhibitor crizotinib." (PMID 36387143, 2022). "We evaluated the safety and efficacy of the anaplastic lymphoma kinase (ALK) tyrosine kinase inhibitor (TKI) brigatinib in Japanese patients with TKI-naive ALK-positive non-small cell lung cancer (NSCLC) from the phase 2, open-label, single-arm, multicenter J-ALTA study." (PMID 36036294, 2022). "Ceritinib is typically used to treat patients with ALK-rearranged non-small cell lung cancer." (PMID 36425467, 2022). "It exhibits robust anti-tumor efficacy in patients with ALK-rearranged non-small cell lung cancer." (PMID 36425467, 2022). "Currently, many targeted drugs are approved for treatment of ALK fusion non-small cell lung cancer." (PMID 36275795, 2022). "Notably, this includes anaplastic lymphoma kinase (ALK) gene rearrangements, which are detected in approximately 3–7% of patients with advanced non-small cell lung cancer (NSCLC)." (PMID 36012123, 2022). "In addition, gatekeeper mutations have been more readily identified after progression on approved TKIs in EGFR-mutant or ALK fusion-positive non-small-cell lung cancer (NSCLC) as compared with RET fusion-positive NSCLC." (PMID 35521769, 2022). "This analysis assesses the efficacy of brigatinib, a next-generation ALK inhibitor in ALK+ advanced non-small cell lung cancer (aNSCLC) included in the brigatinib French Early-Access Program (1 August 2016–21 January 2019), with a focus on post-brigatinib lorlatinib efficacy." (PMID 35406523, 2022). "ALK fusion events are a well-established target for non-small cell lung cancer therapy." (PMID 35593700, 2022). "ALK translocation is present in 4–5% of patients with non-small-cell lung cancer." (PMID 35681698, 2022). "Besides the clinical benefit of crizotinib in ALK-rearranged metastatic non-small cell lung cancer (NSCLC), concerns about its hepatotoxicity have arisen." (PMID 33509141, 2021). "In 2017, a study showed that patients with ALK rearrangements had a three to fivefold higher risk of thrombosis than patients with non-small-cell lung cancer (NSCLC) without ALK rearrangements." (PMID 32885400, 2021). "Recently, somatic mutations of EGFR and BRAF and gene rearrangements of ALK and ROS1 have been recommended for testing before the initial treatment of patients with advanced non-small cell lung cancer (NSCLC) based on the guidelines from major professional organizations." (PMID 34946321, 2021). "The discovery of EGFR mutations and ALK rearrangements also contributed to the development of a new scale of prognostic factors in patients with brain metastases of non-small cell lung carcinoma, taking into account the presence of EGFR mutations or ALK rearrangements." (PMID 33435596, 2021).